SPCS1 (signal peptidase complex subunit 1)
Description:
Component of the signal peptidase complex (SPC) which catalyzes the cleavage of N-terminal signal sequences from nascent proteins as they are translocated into the lumen of the endoplasmic reticulum. Dispensable for SPC enzymatic activity (By similarity). (Microbial infection) Required for the post-translational processing of proteins involved in virion assembly and secretion from flaviviruses such as West Nile virus (WNV), Japanese encephalitis virus (JEV), Dengue virus type 2 (DENV-2), Yellow Fever virus (YFV), Zika virus (ZIKV) and hepatitis C virus (HCV). Plays a key role in the post-translational processing of flaviviral structural proteins prM, E, and NS1. In HCV, it is involved in virion assembly where it promotes the interaction between HCV virus proteins NS2 and E2.
Synonyms: SPC12; HSPC033; YJR010C-A; SPC1
Tractability: Antibody: UniProt predicts a signal peptide or a membrane-spanning region. PROTAC: ubiquitination databases record sites on it; its protein half-life has been measured.
Gene: Protein-coding gene on chromosome 3 (52,704,955 to 52,711,148, forward strand). Ensembl gene ENSG00000114902.
Subcellular location: Endoplasmic reticulum membrane
Subcellular location (Human Protein Atlas): Golgi apparatus; Vesicles
Pathways (Reactome):
Metabolism of proteins: SRP-dependent cotranslational protein targeting to membrane; Synthesis, secretion, and deacylation of Ghrelin; Synthesis, secretion, and inactivation of Glucagon-like Peptide-1 (GLP-1); Synthesis, secretion, and inactivation of Glucose-dependent Insulinotropic Polypeptide (GIP)
Disease: Maturation of DENV proteins; Maturation of hRSV A proteins
Cell-Cell communication: Regulation of CDH1 posttranslational processing and trafficking to plasma membrane
Gene Ontology:
Molecular function: protein binding
Biological process: protein processing; viral protein processing; virion assembly; protein targeting to ER; proteolysis
Cellular component: endoplasmic reticulum membrane; signal peptidase complex; membrane
Genetic constraint (gnomAD): Loss-of-function variants: 10 observed, 17.12 expected, observed/expected ratio (o/e) 0.58, 90% interval 0.36 to 0.99. The upper end of that interval is the gene's LOEUF score, 0.99, which puts it in group 4 of 6, group 1 being the genes least tolerant of losing a copy. Missense variants: 118 observed, 129.87 expected, observed/expected ratio (o/e) 0.91, 90% interval 0.78 to 1.06. Synonymous variants: 47 observed, 44.5 expected, observed/expected ratio (o/e) 1.06, 90% interval 0.83 to 1.35.
Homologues: Orthologues: chimpanzee SPCS1 (100% identical), macaque SPCS1 (99% identical), dog SPCS1 (96% identical), rabbit SPCS1 (96% identical), rat Spcs1 (95% identical), guinea pig SPCS1 (94% identical), pig SPCS1 (94% identical), mouse Spcs1 (67% identical), tropical clawed frog spcs1 (67% identical), zebrafish spcs1 (56% identical), Drosophila melanogaster Spase12 (38% identical), Caenorhabditis elegans spcs-1 (29% identical).
Diseases named in the same sentence as SPCS1 in open-access papers:
SPCS1 is named in the same sentence as 19 diseases in open-access papers, as found by Europe PMC text mining. Sharing a sentence is not in itself a finding about the gene and the disease. The quoted sentences say what the papers report.
depression (2 papers, 2021 to 2025). "The AUC of the nomogram was 0.841, indicating that ITGB5 and SPCS1 are good biomarkers in diagnosing AD with depression." (PMID 40074694, 2025). "The most notable finding is that we identified two predictive genes (ITGB5 and SPCS1) and formed a nomogram for diagnosing AD with depression." (PMID 40074694, 2025). "Although the precise mechanisms of SPCS1's involvement in AD with depression remain incompletely understood, its significance in intracellular protein processing pathways and association with these AD with depression has garnered considerable research interest." (PMID 40074694, 2025). "Furthermore, the nomogram indicated that ITGB5 and SPCS1 are good biomarkers in diagnosing AD with depression." (PMID 40074694, 2025). "Therefore, further investigation is necessary to elucidate the specific mechanisms through which SPCS1 impacts the development of AD with depression." (PMID 40074694, 2025). "Similar to GNL3, SPCS1 and TMEM110 also lie in the 3p21.1 region, and their expression levels were previously shown to be associated with risk variants of schizophrenia, bipolar disorder, and depression." (PMID 34807913, 2021). "Therefore, ITGB5 and SPCS1 were used as predictive biomarkers of AD with depression." (PMID 40074694, 2025). "Moreover, the role of SPCS1 in protein synthesis may impact the expression of cytokines or other inflammatory mediators, which is crucial for understanding the role of SPCS1 in the neuroinflammation of AD with depression." (PMID 40074694, 2025).
Flavivirus Infections (2 papers, 2023 to 2024). Infections with viruses of the genus FLAVIVIRUS, family FLAVIVIRIDAE. "A previous genome-wide CRISPR KO screen uncovered both SPCS1 and SPCS3 as proviral factors for flavivirus infection, and depletion of SPCS1 led to inefficient polyprotein cleavage disrupting flavivirus production." (PMID 39261662, 2024). "A previous genome-wide CRISPR knockout screen uncovered both SPCS1 and SPCS3 as proviral factors for flavivirus infection, and depletion of SPCS1 led to inefficient polyprotein cleavage disrupting flavivirus production." (PMID 37398144, 2023).
lung carcinoma (2 papers, 2010 to 2022). "In addition, hsa-miR-204 and hsa-miR-211, bothpredicted to be associated with SPCS1, are implicated in mechanismsof cell proliferation and metastasis in several types of cancer, including breast,colon, and lung cancer." (PMID 35167647, 2022).
cervical dysplasia (1 paper, 2025). "Additionally, clinical cohort studies are needed to correlate TvAP65/SPCS1 expression levels with HPV persistence and cervical dysplasia in T. vaginalis-positive patients." (PMID 41199321, 2025).
co-infection (1 paper, 2025). "Exploring SPCS1’s broader role in other T. vaginalis-associated pathologies, such as preterm birth or HIV co-infection, could uncover shared mechanisms of host subversion." (PMID 41199321, 2025).
head and neck squamous cell carcinoma (1 paper, 2022). A squamous cell carcinoma that arises from any of the following anatomic sites: lip and oral cavity, nasal cavity, paranasal sinuses, pharynx, larynx, and salivary glands. "SPCS1 expression can be affected by FOXM1-modulated gene promoter methylation in head and neck squamous cell carcinoma." (PMID 35653344, 2022). "In the current study, we aimed to investigate the expression of the five microsomal signal peptidase complex (SPC) subunit genes (SEC11A, SEC11C, SPCS1, SPCS2, and SPCS3) in head and neck squamous cell carcinoma (HNSC) and to explore their prognostic value." (PMID 35653344, 2022).
Rotavirus infection (1 paper, 2025). Infection with any of the rotaviruses. "SPCS1 does not regulate viral RNA and protein levels during rotavirus infection." (PMID 41279876, 2025).
schizophrenia (1 paper, 2021). A major psychotic disorder characterized by abnormalities in the perception or expression of reality. "In fact, CEWAS also detected GNL3, SPCS1, and TMEM110 for intelligence with z-scores having opposite signs compared to schizophrenia, which aligns with how risk alleles in these loci were previously shown to correlate with lower cognitive test scores." (PMID 34807913, 2021).
stomach cancer (1 paper, 2024). "The expression of EIF4E, EXOSC1, IARS1, IGFBP1, and SPCS1 was found to be upregulated in stomach cancer cell lines, while TSPYL2 and TUBB2A showed downregulated expression." (PMID 38700505, 2024). "Based on the TCGA cohort, we integrated clinical factors such as age, stage, N stage, SPCS1, IGFBP1 and TSPYL2 to construct a nomogram to enhance survival prediction for patients with stomach cancer." (PMID 38700505, 2024).
Tetralogy of Fallot (1 paper, 2016). A congenital cardiac malformation comprising pulmonary stenosis, overriding aorta, ventricular septum defect, and right ventricular hypertrophy. "Pnn, Spcs1, Ddx39, Mcm7 and Phkb mRNAs were downregulated in HLHS patient RVs when compared to control RVs obtained from Tetralogy of Fallot patients (black bar vs white bar)." (PMID 27485310, 2016).
viral infection (1 paper, 2013). "It seemed that knockdown of SPCS1 had a higher impact on the later stage of viral infection compared to either SPCS2 or SPCS3, which are possibly involved in the catalytic activity of the signal peptidase." (PMID 24009510, 2013).
ZIKV infection (1 paper, 2020). "SPC, especially SPC subunit 1 (SPCS1), is crucial for ZIKV pathogenesis as knocking out SPCS1 in 293 T cells significantly reduced ZIKV infection and drastically impaired the production of infectious ZIKV particles." (PMID 31959174, 2020).
infection (7 papers, 2013 to 2025). The state of being infected such as from the introduction of a foreign agent such as serum, vaccine, antigenic substance or organism. "Strikingly, dual knockdown of TvAP65 and SPCS1 synergistically suppressed infection (54.64 ± 0.39% reduction, P < 0.001), surpassing the effects of individual knockdowns." (PMID 41199321, 2025). "Genome-wide CRISPR screening has identified SPCS1 as a key host factor in the processing of viral proteins that are made as polyproteins containing internal SSs and TM segments during infection by viruses of the flavivirus family." (PMID 34125229, 2021). "SPCS1 siRNAs or control siRNA were transfected into Huh7.5.1 cells followed by infection with JEV or HCVcc." (PMID 24009510, 2013). "To determine the stage of the viral replication cycle was affected by SPCS1, we assessed viral infectivity by measuring NSP5 mRNA and VP6 protein levels in WT and SPCS1 KO HEK293T cells at 4, 8 and 12-hour post infection." (PMID 41279876, 2025). "Similar to the results obtained with RRV with 7.5-fold reduction in titers, infection with simian strain SA11 or bovine strain UK also showed 11-fold and 9-fold reduction viral titers in SPCS1 KO cells compared with WT cells, respectively." (PMID 41279876, 2025). "The signal peptidase complex (SPCS) components were also shown to be important during infection of human (293 T and HeLa) and insect (Drosophila and mosquito) cells, with SPCS1 important for WNV, DENV, ZIKV, JEV, YFV, and HCV infection." (PMID 34696709, 2021).
SPCS1 also shares sentences with these, for which no sentence is quoted: bipolar disorder (1 paper); cancer (1); cervical cancer (1); liposarcoma (1); osteoarthritis (1); sarcoma (1).